RAB5B (RAB5B, member RAS oncogene family)
Diseases named in the same sentence as RAB5B in open-access papers (continued):
Sharing a sentence is not in itself a finding about the gene and the disease.
tumor (continued). "Moreover, we observed a downregulation of RAB5B and upregulation of RAB7A, two small GTPases closely linked to intracellular transport and tumor progression." (PMID 40080350, 2025). "This suggests that RAB5B may influence cancer progression and patient prognosis by modulating the tumor microenvironment." (PMID 40842984, 2025). "The antagonistic relationship between RAB7A and RAB5B may represent a defensive mechanism employed by tumor cells to counteract the inhibitory effects of BmK-M9, which could disrupt vesicular transport processes critical for tumorigenesis." (PMID 40080350, 2025). "Our study revealed the key role of RAB5B in tumor biomarkers." (PMID 40842984, 2025). "Through ESTIMATE analysis, it was observed that the expression level of RAB5B was negatively correlated with the matrix score, immune score, and ESTIMATE score in 33 tumor microenvironment cases, further confirming RAB5B’s significant role in regulating the tumor microenvironment." (PMID 40842984, 2025). "For example, tumor suppresser lncRNA-APC1 interacts with Rab5b mRNA and reduces mRNA stability." (PMID 36320056, 2022). "The upregulation of SIAH1, similar to RAB5B, may function as a defense mechanism in tumor cells." (PMID 40080350, 2025). "In addition, the abnormality of RAB5B may interfere with other important signal pathways in cells and further aggravate the malignant progress of tumor." (PMID 40842984, 2025). "Furthermore, we have performed genome-wide variation analysis and cancer prognosis evaluation to explore the intrinsic relationships between RAB5B and key factors such as DNA methylation, CNV, tumor mutation burden (TMB), microsatellite instability (MSI), and immune infiltration." (PMID 40842984, 2025). "Therefore, it is hypothesized that in patients with ACC and THYM, RAB5B may exert its biological function by modulating the number of M2-type macrophages in the tumor microenvironment, thereby adversely impacting patient prognosis." (PMID 40842984, 2025). "This suggests that RAB5B may influence the tumor immune environment through these pathways." (PMID 40842984, 2025). "The study demonstrated that RAB5B expression levels have complex and diverse correlations with core elements of various tumor types, including immune regulatory factors, immune cell infiltration, tumor microenvironment characteristics, TMB, and MSI, leading to different effects on tumor immunity." (PMID 40842984, 2025). "Additionally, RAB5B expression was negatively correlated with several immune-related pathways, such as B cell-mediated immunity, immunoglobulin-mediated immune responses, and phagocytosis, which are crucial for tumor cell stress response, repair mechanisms, and cell cycle regulation." (PMID 40842984, 2025). "Although we observed upregulation of all three Rab5 isoforms (Rab5A, Rab5B, Rab5C) in HCC, their individual contributions to lipid metabolism and tumor progression remain undefined." (PMID 40894643, 2025). "In addition, this discovery may also indicate that the high expression of RAB5B is closely related to the inhibitory state in tumor microenvironment and the weakening of immune response, which may provide favorable conditions for the escape and further development of tumor cells." (PMID 40842984, 2025). "By down regulating Rab5b, lncRNA-APC1 inhibits the production of tumor-promoting exosomes and progression of colorectal carcinoma." (PMID 36320056, 2022). "Therefore, future research should focus on influencing tumor microenvironment or MSI by regulating RAB5B, in order to fully explore the expression of RAB5B in predicting the efficacy of immunotherapy and accurately stratifying the patient population." (PMID 40842984, 2025). "Additionally, the study explored potential links between RAB5B and factors such as CNV, DNA methylation, MSI, TMB, and immune cell infiltration in the tumor microenvironment." (PMID 40842984, 2025).
tumor (continued). "Recent data support the high level of versatility of the technique, with the identification of a series of housekeeping proteins, such as Rab5b, CD81, and CD63, and tumor-specific markers, such as PSA, but also surrogate tumor markers, such as Cav-1 and carbonic anhydrase." (PMID 37296842, 2023). "The early endosomal autoantigen EEA1 was found in a yeast two-hybrid system to interact directly with RAB5B in a GTP-dependent matter, independent of intrinsic GTPase activity; in tumor cells, exosomes tended to localize with EEA1." (PMID 28589855, 2017).
cancer (7 papers, 2008 to 2025). A tumor composed of atypical neoplastic, often pleomorphic cells that invade other tissues. "For each cancer type, one-way Cox regression analysis was utilized, based on data from the TCGA database, to investigate the association between RAB5B expression levels and the prognosis of various cancers." (PMID 40842984, 2025). "High expression of RAB5B is associated with cancer progression and poor prognoses in numerous cancer types, including pancreatic, breast and ovarian cancer." (PMID 33154765, 2020). "As scientific research advances, there is substantial evidence to suggest that thorough exploration of the RAB5B gene and its associated pathways may offer novel approaches and strategies for cancer diagnosis, treatment, and prevention." (PMID 40842984, 2025). "Additionally, analysis revealed variations in RAB5B gene mutation frequency across different cancer types." (PMID 40842984, 2025). "Molecular docking and experimental validation showed that downregulating RAB5B inhibited cell proliferation and reduced cancer cell migration." (PMID 40842984, 2025). "The CNV distribution of the RAB5B gene across distinct cancer types is illustrated using pie charts, with color-coding distinguishing different CNV categories." (PMID 40842984, 2025). "Through in-depth exploration of the cBioPortal database, genomic alterations of the RAB5B gene across various cancer types were identified." (PMID 40842984, 2025). "By precisely regulating the expression or function of RAB5B, it is anticipated that the substance transport chain of cancer cells can be interrupted, thereby inhibiting their malignant behaviors such as proliferation, invasion, and metastasis." (PMID 40842984, 2025). "In order to explore the significance of RAB5B in malignant tumors, the expression level of RAB5B was carefully examined in 33 cancer types using comprehensive data sets obtained from TCGA and GTEx databases." (PMID 40842984, 2025). "Studies have identified RAB5B as a robust prognostic biomarker for cancer, capable of predicting immunotherapy outcomes." (PMID 40842984, 2025). "Integrative genomic analyses using cBioPortal and Gene Set Cancer Analysis (GSCA) further characterized RAB5B’s genomic alterations and cancer-specific profiles." (PMID 40842984, 2025). "Results from CCK-8 assays demonstrated significantly reduced proliferation in RAB5B-deficient cells compared to control groups, highlighting the importance of RAB5B in regulating cancer cell proliferation." (PMID 40842984, 2025). "Our research has brought novel insights into the application of RAB5B in oncology, and clearly revealed its close relationship with immune cells and immune-related molecules in various cancer types." (PMID 40842984, 2025). "The findings reveal a substantial correlation between RAB5B expression levels and the extent of immune cell infiltration across various cancer types, strongly supported by experimental evidence." (PMID 40842984, 2025). "Based on the median expression level of RAB5B in various cancer types, samples were categorized into low and high RAB5B groups." (PMID 40842984, 2025). "Studies have shown that in many cancers, the abnormal expression and function of RAB5B are closely related to the progress of the disease." (PMID 40842984, 2025). "RAB5B is crucial not only for maintaining normal cellular transcription but also for cancer initiation, progression, and deterioration." (PMID 40842984, 2025). "Firstly, data resources from the TCGA and GTEx databases were utilized to conduct a comprehensive and systematic analysis of the expression patterns of RAB5B across various cancers." (PMID 40842984, 2025). "As research progresses, the mechanisms of RAB5B in cancer will be elucidated, offering new insights and targets for cancer diagnosis, treatment, and prognosis assessment." (PMID 40842984, 2025).
cancer (continued). "The impact of RAB5B silencing on cell proliferation and migration was investigated to better understand its role in cancer progression." (PMID 40842984, 2025). "GSVA further explored the relationship between RAB5B and immune-related pathways across different cancer types, offering new insights into RAB5B’s role as an immunomodulator." (PMID 40842984, 2025). "For instance, targeting RAB5B through small molecule inhibitors or gene editing technology offers a means to further explore its potential applications in cancer therapy." (PMID 40842984, 2025). "The results show that there is a significant correlation between the expression level of RAB5B and the prognosis of cancer patients." (PMID 40842984, 2025). "RAB5B exhibits varying expression patterns and functions across different cancers." (PMID 40842984, 2025). "RAB5B can change the migration and adhesion characteristics of cancer cells by affecting vesicle transport and signal transduction in cells, thus promoting the spread and metastasis of cancer cells and increasing the malignant degree and prognosis risk of cancer." (PMID 40842984, 2025). "A significant correlation between RAB5B and the prognosis of most cancers is evident." (PMID 40842984, 2025). "It focused on genomic variations of RAB5B across different cancers and their prognostic impact." (PMID 40842984, 2025). "Furthermore, they reinforce the position of RAB5B as a reliable indicator for prognosis evaluation in various cancers." (PMID 40842984, 2025). "At the same time, the in-depth study of the complex interaction between RAB5B and other signal pathways will also help us to reveal the mystery of cancer occurrence and development more comprehensively and open up new ideas and ways for the development of precision medicine." (PMID 40842984, 2025). "RAB5B is regarded as a potential therapeutic target in cancer research." (PMID 40842984, 2025). "Through sequence function enrichment analysis, the function of RAB5B in cancer was discussed." (PMID 40842984, 2025). "In addition, our research results also provide useful clues for further exploring the potential role of RAB5B in cancer immunotherapy." (PMID 40842984, 2025). "Despite achieving these preliminary research outcomes, many unknowns regarding the specific molecular mechanism of RAB5B in other cancers remain to be further explored." (PMID 40842984, 2025). "However, current research on RAB5B predominantly focuses on individual cancer types, and its comprehensive roles and therapeutic relevance across diverse malignancies remain to be further explored." (PMID 40842984, 2025). "In addition, RAB5B is also involved in the regulation of autophagy, which further broadens its potential role in cancer research." (PMID 40842984, 2025). "Hsa-miR-130a-3p seems to have a cancer-promoting function in connection with RAB5B." (PMID 35409043, 2022). "RAB5B regulates cell adhesion and migration by promoting Rac1 activation and cancer cell migration." (PMID 33154765, 2020). "Notably, RAB5B is also involved in regulating the metastasis and invasion of cancer cells." (PMID 40842984, 2025). "However, the expression of RAB5B in other eight cancers is abnormally increased, which is quite different from the previous view that the expression of RAB5B is inhibited in invasive malignant tumors, thus suggesting that RAB5B may play a completely different role in many cancers." (PMID 40842984, 2025). "Cancer cell lines (MCF-7, SK-Hep-1) with RAB5B knockdown via siRNA were employed to explore its biological functions." (PMID 40842984, 2025). "RAB5B has the potential to decrease TMB and MSI in certain cancers through the MMR system." (PMID 40842984, 2025). "PPM1A, SNRPN, RAB5B, and CAPG were also reported to be related to cancer." (PMID 18237428, 2008).
cancer (continued). "Specifically, it was found that the expression of RAB5B is positively correlated with a range of immunomodulatory genes, encompassing MHC molecules, immune activating factors, immunosuppressive molecules, chemokines, and their receptor proteins, among others, in almost all cancer types." (PMID 40842984, 2025). "Leveraging extensive cancer data from the TCGA database, with a specific focus on ACC and THYM cancers, the study identified a negative correlation between RAB5B expression and the infiltration levels of NKT, CD8+T, MDSC, Tfh, and γ/δ T cells." (PMID 40842984, 2025).
infection (3 papers, 2014 to 2024). The state of being infected such as from the introduction of a foreign agent such as serum, vaccine, antigenic substance or organism. "We selected Rab5b, Rab11b, Rab8b and Rab11FIP1 for further characterisation in response to a ΔsdhA infection." (PMID 32096265, 2020). "On the other hand, infection with MHV-S2′FCS was significantly diminished by downregulation of the early endosomal proteins RAB5B and RAB5C, but not of the late endosomal proteins RAB7A and RAB7B or the HOPS complex components VPS11 and VPS41 (blue bars)." (PMID 25375324, 2014).
RAB5B also shares sentences with these, for which no sentence is quoted: hypothyroidism (2 papers); Angelman syndrome (1); autism (1); basal cell carcinoma (1); deep vein thrombosis (1); eczema (1); essential hypertensive (1); gastric cancer (1); gastroduodenal ulcer (1); inflammatory bowel disease (1); nasopharyngeal carcinoma (1); neurodegenerative disease (1); Obesity (1); polycystic ovary syndrome (1); prostate carcinoma (1); prostate hyperplasia (1); type 2 diabetes mellitus (1); vitiligo (1).